NLRP3 (NLR family pyrin domain containing 3)
Diseases named in the same sentence as NLRP3 in open-access papers (continued):
Sharing a sentence is not in itself a finding about the gene and the disease.
gout (continued). "SLC3037, an NLRP3 inhibitor that blocks NEK7 [never in mitosis A (NIMA)-related kinase 7 (NEK7) critical in NLRP3 oligomerization] binding to NLRP3, shows promise as a novel agent for diseases associated with NLRP3 inflammasome activation like gout." (PMID 39968300, 2025). "The findings indicate that curcumin may inhibit the assembly and activation of the NLRP3 inflammasome by directly targeting and disrupting the interaction between NEK7 and NLRP3, thus providing insight into curcumin's ability to mitigate gout‐related damage and inflammation." (PMID 41035515, 2025). "Gout is a form of sterile inflammatory arthritis in which monosodium urate (MSU) crystals deposit and provoke a neutrophil-predominant response, primarily driven by activation of the NACHT, leucine-rich repeat, and pyrin domain-containing protein 3 (NLRP3) inflammasome." (PMID 41090769, 2025). "Targeting NLRP3 through potentially effective drugs such as natural products, novel compounds, and non-coding RNAs (ncRNAs) for the treatment of mouse models of MSU-induced gouty arthritis may be important for the treatment of gouty arthritis." (PMID 40444241, 2025). "Furthermore, cardamonin and mastoparan M could ameliorate joint inflammation by suppressing NLRP3 inflammasome activation in iron-overload-induced arthritis and MSU-crystal-induced gouty arthritis, respectively." (PMID 39852153, 2025). "Besides reducing uric acid levels in gout treatment, febuxostat, but not allopurinol, prevents NLRP3 inflammasome assembly and blocks IL-1β production by macrophages." (PMID 40399065, 2025). "In this context, targeting the NLRP3 ATP hydrolysis motifs (Walker A and B) may hold promise in alleviating NCOA6-induced NLRP3 hyperactivation and could be a novel treatment strategy for inflammatory diseases dependent on NLRP3, including gouty arthritis." (PMID 38195836, 2024). "Our data showed that, in the process of gout disease, the expression of XOD increases, which increases the level of uric acid in the body, disrupts the balance of oxidative stress, generates a large amount of ROS, activates the NLRP3 inflammasome, and release IL-1β." (PMID 36569836, 2022). "NLRP3 inflammasome activation by MSU crystal inducers resulting from phagocytosis by macrophages and neutrophils may have implications for the inflammatory pathophysiology of gouty arthritis." (PMID 35400961, 2022). "In gouty arthritis, Lian and colleagues elucidated that circHIPK3 was enriched in mononuclear cells of synovial fluid, which strikingly repressed miR-561 and miR-192, and thereby facilitated pro-inflammatory functions of toll-like receptor 4 (TLR4) and NLR family pyrin domain containing 3 (NLRP3)." (PMID 36292157, 2022). "Based on the pharmacodynamics of PIP as an anti-inflammatory that disrupts the NLRP3 inflammasome cascade, in vivo experiments were done to demonstrate the preventive (protocol I) and curative (protocol II) action of PIP on anti-arthritis gout resulting from MSU deposition." (PMID 35400961, 2022). "Our data showed that, in the process of gout disease, the expression of xanthine oxidase (XOD) has been increasing, which increases the level of uric acid, disrupts the balance of oxidative stress, generates a large amount of ROS, activates the NLRP3 inflammasome, and release IL-1β." (PMID 36569836, 2022). "NLRP3 inflammasome inhibitors and IL-1 inhibitors, such as anakinra (an IL-1R antagonist), rilonacept (IL-1 TRAP), and canakinumab (monoclonal anti-IL-1β antibody), have been tested in clinical trials and showed efficacy in the treatment of acute and chronic gout patients." (PMID 36387275, 2022). "However, its upregulation can also promote gout pathogenesis through the negative effect of cAMP on the NLRP3 inflammasome." (PMID 34925366, 2021).
gout (continued). "Therefore, we investigated whether loganin has suppressive effects on the NLRP3 inflammasome activation induced by MSU crystals and may consequently prevent gout inflammation in mouse primary macrophages and mouse acute gout models." (PMID 33670601, 2021). "Therefore, cardamonin could reduce the level of NLRP3, caspase 1, IL-1β, and COX-2 under MSU stimulation, which might help for gout treatment." (PMID 34577821, 2021). "Interestingly, expression of the NLRP3 inflammasome components was not affected by TLR2 priming or urate crystal activation in gout monocytes." (PMID 34992596, 2021). "Our results indicate that wedelolactone promotes the Ser/Thr phosphorylation of NLRP3 to inhibit inflammasome activation and pyroptosis partly through potentiating PKA signalling, thus identifying its potential use for treating MSU‐induced peritonitis and gouty arthritis." (PMID 32656909, 2020). "However, the detailed mechanism of wedelolactone regulating NLRP3 inflammasome and pyroptosis has not been fully clarified, and the influence on gouty arthritis has not been addressed before." (PMID 32656909, 2020). "Importantly, wedelolactone could alleviate NLRP3‐related inflammation in MSU‐induced peritonitis and gouty arthritis." (PMID 32656909, 2020). "As the NLRP3 inflammasome is a key element in the MSU crystalloid-induced inflammatory response, strategies that block its activation or affect its activity could reduce gout inflammation." (PMID 31455356, 2019). "Monosodium urate (MSU) microcrystals present in bone tissues of chronic gout can be ingested by nonprofessional phagocytes like osteoblasts (OBs) that express NLRP3 (nucleotide-binding domain and leucine-rich repeat region containing family of receptor protein 3)." (PMID 24456929, 2013). "Interestingly, celastrol is reported to inhibit the activation of the NLRP3 inflammasome in LPS-induced liver damage and monosodium urate-induced gouty arthritis by blocking the de-ubiquitination of NLRP3 and cleavage of pro-IL-1β, without affecting the total protein level of NLRP3." (PMID 40391077, 2025). "Therefore, we speculate that there may be negative feedback regulation in patients with gout, when MSU crystals act on the NLRP3 inflammasome to cause acute inflammation." (PMID 33935726, 2021). "However, despite the discovery of the NLRP3 inflammasome and its role as a Pattern Recognition Receptor linking the detection of a danger signal (MSU) to IL-1β secretion in vitro, the precise mechanisms leading to joint inflammation in gout patients are still poorly understood." (PMID 32104502, 2020). "Importantly, our results showed that the beneficial effects of Ori on peritonitis, gouty arthritis and type 2 diabetes were absent in Nlrp3-/- mice, suggesting that the in vivo anti-inflammatory activity of Ori depends on its inhibitory effects on NLRP3 inflammasome." (PMID 29959312, 2018). "Gout is an acute, nonseptic arthritis induced by monosodium urate (MSU) crystals, with its core pathogenesis involving NLRP3 inflammasome activation and massive release of IL‐1β." (PMID 41362701, 2025). "Simiao decoction and its related FMT significantly reduced the production of NLRP3, caspase-1 and ASC, but allopurinol only reduced the production of ASC, and its related FMT had no significant influence on NLRP3 inflammasome in gouty arthritis mice." (PMID 37344836, 2023). "Polymorphisms in CARD8 leading to decreased expression of CARD8 were also connected to the severity of rheumatoid arthritis and gout; however, in this case, CARD8 does not act as an inflammasome sensor but rather as a potential inhibitory regulator of NLRP3." (PMID 35629398, 2022). "For example, gout arthritis is characterized by hyperuricemia-derived monosodium urate (MSU) deposition followed by NLRP3 inflammasome activation, while MSU alone does not trigger gout flare." (PMID 34150848, 2021).
gout (continued). "Moreover, NLRP3, lacking half of its LRR domain, lost its ability to respond to MSU, a common trigger used to mimic gout." (PMID 39195255, 2024). "However, it is interesting to note that Clec12a signalling does not affect the NLRP3 inflammasome pathway, so this CLR is an unlikely target for gout therapy." (PMID 25975607, 2015). "In sharp contrast, mice with and without complete Freund’s adjuvant (CFA)-induced arthritis, which is not NLRP3 inflammasome-specific, showed no such difference in the thickness of the paw and ankle, indicating that NCOA6 may specifically contribute to gouty arthritis in vivo." (PMID 38195836, 2024).
Obesity (488 papers, 2012 to 2026). Accumulation of substantial excess body fat. "A key family of inflammatory mediators implicated in obesity-induced inflammation is the NOD-like receptor protein 3 (NLRP3) inflammasome complex." (PMID 40145973, 2026). "Strong evidence suggests that the NLRP3 inflammasome is a key mediator of inflammation and insulin resistance (IR) associated with obesity." (PMID 41596350, 2026). "Addressing these multiple inflammatory pathways, especially the NLRP3 inflammasome, has been identified as a promising therapeutic strategy for alleviating metabolic complications associated with obesity." (PMID 41226484, 2025). "Despite recent studies highlighting the pivotal role of NLRP3-induced pyroptosis in obesity-induced cardiac dysfunction, the underlying molecular mechanisms remain poorly understood." (PMID 40430076, 2025). "Given the strong association between obesity, NLRP3 inflammasomes, and the progression of HFpEF, these findings are significant." (PMID 40182777, 2025). "In animal models, obesity and asthma induced by a high-fat diet were associated with an increased NLRP3 inflammasome response and eosinophil-mediated inflammation in the airways." (PMID 41007770, 2025). "Studies have demonstrated that high-fat diets induce NLRP3 activation, which contributes to obesity and associated metabolic disorders." (PMID 41411269, 2025). "Obesity increases the risk of endometrial cancer, and the NLRP3-IL-1β pathway plays a crucial role in adipose tissue (AT)-induced inflammation and the development of obesity-related comorbidities." (PMID 40718836, 2025). "Obesity-associated stimuli such as lipotoxicity, mitochondrial dysfunction and increased extracellular ATP lead to activation of the NLRP3 inflammasome in both adipocytes and resident immune cells." (PMID 40943225, 2025). "In contrast, deletion of NLRP3 reverses the symptoms in mouse models of obese asthma, suggesting targeting NLRP3 inflammasome has important potential in obesity‐associated airway allergic diseases." (PMID 40329860, 2025). "NLRP3 inflammasome senses danger signals associated with obesity and participates in obesity-induced inflammation and insulin resistance." (PMID 40764506, 2025). "Of note, an overactivation of canonical caspase‐1‐dependent NLRP3 inflammasome pathway has been reported to contribute to the immune/inflammatory responses associated with obesity." (PMID 39287080, 2025). "In the present study, we investigated the involvement of NLRP3 inflammasome in the intestinal epithelial barrier (IEB) changes associated with obesity, and its role in the interplay between enteric glia and intestinal epithelial cells (IECs)." (PMID 39287080, 2025). "In conclusion, our data support a model wherein ongoing inflammation (including hypothalamic gliosis) represents a druggable mechanism implicated in obesity pathogenesis, one that can be ameliorated by NLRP3 inhibition." (PMID 40304241, 2025). "Elevated circulating branched-chain amino acids (BCAAs), associated with obesity and insulin resistance, have been shown to induce mitochondrial stress and activate the NLRP3 inflammasome in macrophages." (PMID 41488670, 2025). "A recent study revealed that fat mass and obesity-associated proteins reduce NLRP3-triggered pyroptosis and inflammasome activation by destabilizing Cbl proto-oncogene mRNA through the inhibition of m6A modification." (PMID 40307577, 2025). "In this context, NLRP3 inflammasome is emerging as critical player in the pathogenesis of inflammatory responses associated with obesity." (PMID 39287080, 2025). "NLRP3 activation is associated with diseases such as type 2 diabetes, obesity, Alzheimer’s, Parkinson’s, cancers, and CKD." (PMID 40725180, 2025). "The NLRP3 inflammasome has emerged as a major therapeutic target to limit pro-inflammatory IL-1β activity in obesity-associated metabolic disorders." (PMID 39532538, 2025).
Obesity (continued). "Whole-body deficiency of MLKL, NLRP3, or CyPD also prevented obesity-induced, or high-fat diet (HFD)-induced insulin resistance and glucose intolerance." (PMID 40216765, 2025). "Synovial inflammation is involved in OA caused by aging, obesity, injury, and mechanical load, and NLRP3-mediated synovial cell pyroptosis is an important factor leading to inflammation." (PMID 40919498, 2025). "Obesity and insulin resistance have been associated with increased NLRP3 expression in adipose tissue." (PMID 40149869, 2025). "Obesity is characterized by chronic pro-inflammatory conditions, with the NLRP3 inflammasome pathway being closely linked to this process." (PMID 40004007, 2025). "Prior studies have concluded that NLRP3 is activated by danger-associated molecular proteins (DAMPs) like higher blood glucose or cholesterol and actively contributes to obesity-induced inflammation and insulin resistance." (PMID 38702410, 2024). "Obesity and obesity-associated type 2 diabetes are considered metabolic syndromes because of their chronic inflammatory nature involving NLRP3 inflammasome activation." (PMID 38945951, 2024). "Homozygous NLRP3 knockout high‐fat diet (HFD)–induced obese mice exhibited reduced AF susceptibility compared with HFD controls, suggesting obesity‐mediated increased NLRP3 activity promotes AF." (PMID 38156451, 2024). "The NLRP3 inflammasome is also strongly associated with other pro-inflammatory conditions, such as obesity." (PMID 38702410, 2024). "Among the factors influencing inflammation associated with obesity, the NLRP3 inflammasome, one of the most well-studied and characterized inflammasomes, has emerged as a potential central hub that assembles in response to cellular perturbations." (PMID 38895630, 2024). "HFD-fed mice with obesity had significantly increased taurine-conjugated BAs, but these affects were nearly abrogated in NLRP3-deficiency." (PMID 38978699, 2024). "Human and animal studies have shown that obesity and insulin resistance are linked to an increase in the NLRP3 inflammasome in adipose tissue." (PMID 38317257, 2024). "In the context of obesity, NLRP3 has been observed to play a significant role in the development of obesity and the associated inflammatory processes." (PMID 38562155, 2024). "Our study confirms that aberrant NLRP3 inflammasome activation in cardiomyocytes worsens obesity‐associated cardiomyopathy and implicates inhibition of NLRP3 inflammasome as a potent therapeutic approach for obesity cardiomyopathy." (PMID 39604027, 2024). "The mRNA expression levels of NLRP3 and the macrophage marker Cd11c in adipocytes showed that obesity is related to NLRP3 induction, which can cause a lipid-loaded macrophage response." (PMID 38945951, 2024). "A prior study implicated a pivotal role for VAT NLRP3-induced signaling in driving obesity-induced cognitive deficits; these effects reflected IL-1-mediated microglial activation." (PMID 38685031, 2024). "Exercise was reported to reduce plasma glucose levels and relative abundance of Proteobacteria, but increased that of Blautia, Dialister, and Roseburia, and inhibited the activation of the obesity-associated NLRP3 signaling pathway in obese pediatric patients." (PMID 38585649, 2024). "Studies on insulin resistance have demonstrated the ability of NLRP3 to recognize obesity-induced danger-associated molecular patterns." (PMID 38945951, 2024). "In essence, obesity instigates pyroptosis through the activation of the NLRP3 inflammasome, a process that has previously been linked to the progression of osteoarthritis (OA)." (PMID 38532994, 2024). "The NLRP3 inflammasome is associated with a variety of human diseases, including Alzheimer’s disease, obesity, rheumatoid arthritis, asthma, nonalcoholic fatty liver disease, and autoimmune encephalitis." (PMID 38355571, 2024). "In obesity-related asthma, heightened oxidative stress and NLRP3 inflammasome activation in airways are implicated in symptom manifestation." (PMID 38762465, 2024).